H19 (H19 imprinted maternally expressed transcript)
Diseases named in the same sentence as H19 in open-access papers (continued):
Sharing a sentence is not in itself a finding about the gene and the disease.
breast cancer (continued). "MCF-7/AdrVp breast cancer cells multi-resistant to several treatments showed a more abundant expression of H19 compared to parental MCF-7 cells." (PMID 33335214, 2020). "Highly up-regulated of H19 was demonstrated in a variety of tumors including colorectal cancer, hepatocellular cancer, breast cancer, lung cancers, and RCC." (PMID 32509581, 2020). "Our findings demonstrate that lncRNA H19 was more abundant in breast cancer cells, particularly in TNBC cells, than in normal mammary epithelial cells." (PMID 32514245, 2020). "This increase in LIN28 expression further potentiates H19 expression, leading to the feedback circuit that acts to maintain the stem cell state in breast cancer." (PMID 32146726, 2020). "The lncRNA H19 can modulate ER function as it has been shown to suppress the ER-activated Wnt signaling pathway in breast cancer cells." (PMID 32759784, 2020). "A previous study has shown that DNMT1 with high expression greatly reverses the suppressive effects of H19 silence on cell proliferation and invasion in breast cancer." (PMID 32918845, 2020). "In connection with the phenotypes linked to the EMT, we further investigated the involvement of H19 in the regulation of breast cancer stem cells." (PMID 32610610, 2020). "While H19 overexpression developed doxorubicin-resistant in breast cancer cells both in vitro and in vivo." (PMID 32345117, 2020). "Enhanced lncRNA H19 expression in breast cancer cells lines induces G1/S cell cycle transition while lncRNA H19 depletion blocks S-phase entry and proliferation." (PMID 32514245, 2020). "In breast cancer, patient plasma H19 levels were elevated, with an sensitivity of 0.81 (AUC, area under the curve), higher than traditional diagnostic biomarkers." (PMID 33330574, 2020). "Our results showed chemotherapy-resistant breast cancer tissue specimens exhibited generally higher H19 levels compared with chemotherapy-sensitive tissues." (PMID 32345117, 2020). "We showed that both H19 and miR-675 increase the invasive capacities of breast cancer cells in xenografted transgenic zebrafish models." (PMID 32610610, 2020). "To compare our findings with H19 basal levels in different established breast cancer cellular lines, we used the MCF-7 and MDA-MB-231 breast cancer cells present in our research unit." (PMID 33335214, 2020). "H19 regulates the tumorigenesis and progression of breast cancer by modulating the gene expressions at multiple levels: transcriptional, post-transcriptional and epigenetically." (PMID 33291485, 2020). "We extended the current knowledge by highlighting the role of H19 in the chemoresistance of breast cancer for the first time." (PMID 32345117, 2020). "Some lncRNAs were considered to be beneficial prognostic indicators to predict prognosis in breast cancer; for instance, lncRNA GACAT3 predicted poor prognosis, and lncRNA H19 was associated with poor prognosis and promoted cancer stemness." (PMID 32967061, 2020). "The aim of this work was to determine the implication but, also, the relative contribution of H19 and miR-675 to the enhancement of breast cancer metastatic potential." (PMID 32610610, 2020). "Quantitative real-time PCR (qRT-PCR) analyzed H19 expression in chemotherapy-resistant and sensitive breast cancer tissues." (PMID 32345117, 2020). "In this study, we observed that the expression of H19 was substantially upregulated in tamoxifen-resistant breast cancer cell line and tumor tissues, and knockdown of H19 enhanced the sensitivity to tamoxifen both in vitro and in vivo." (PMID 31340867, 2019). "The H19 was upregulated in many tumors including esophageal squamous cell carcinoma, lung cancer, gastric cancer, and breast cancer, and H19 overexpression contributes to poor prognosis in these patients." (PMID 31299871, 2019). "In this study, it was shown that the overexpression of H19 in tamoxifen-resistant breast cancer cells serves as a promising predictive biomarker for clinical patients." (PMID 31340867, 2019).
breast cancer (continued). "Experimental results showed that knocking out H19 significantly increased MDR1 and MRP4 in Dox-resistant breast cancer cells, which identified the role of H19 in breast cancer resistance." (PMID 31777598, 2019). "In this study, we revealed that the expression of H19 is substantially upregulated in tamoxifen-resistant breast cancer cell line and tumor tissues, and silencing H19 sensitizes MCF7/TAMR cells to tamoxifen treatment both in vitro and in vivo." (PMID 31340867, 2019). "For instance, in breast cancer, H19 differentially sponges miR-200b/c and let-7b to mediate EMT and MET plasticity." (PMID 31160577, 2019). "H19 acts as a precursor of miR-673 in breast cancer to enhance breast cancer cell proliferation and invasion." (PMID 30744670, 2019). "H19 promotes cell cycle progression in breast cancer, while the depletion of H19 RNA arrests breast cancer cells in the pre-S-phase of the cell cycle." (PMID 30890582, 2019). "H19 plays important roles in proliferation, metastasis, chemoresistance, and stem cell maintenance of breast cancer cells." (PMID 31340867, 2019). "Emerging studies have reported that lncRNA H19 was upregulated in various cancers, such as nonsmall cell lung cancer, bladder cancer, breast cancer, and gastric cancer." (PMID 31016202, 2019). "Further functional experiments found that the expression level of H19 in breast cancer tissues was higher than that in normal tissues, and rs217727 CT or TT genotype was helpful to improve the expression level of H19 (P<0.001, 12]." (PMID 31752724, 2019). "Recent studies have reported that ER promotes H19 expression, and H19 is upregulated in ER+ breast cancer." (PMID 31340867, 2019). "H19 has been found to re-express during tumorigenesis in many kinds of tumors, such as breast cancer, lung cancer, invasive cervical carcinomas, esophageal cancer, and bladder cancer." (PMID 30890582, 2019). "In this study, we elucidate how H19 regulates autophagy in the setting of tamoxifen-resistant breast cancer." (PMID 31340867, 2019). "Because tamoxifen-resistant breast cancers rarely harbor ESR1 mutations, which confer only partial resistance to tamoxifen, the upstream molecular regulator of H19 in developing tamoxifen resistance remains to be investigated." (PMID 31340867, 2019). "We first identified the clinical indications of Let‐7 family and Wnt signalling pathway in patients with breast cancer; we used public big data to primarily establish the proposed interactions between Let‐7, H19 and Wnt signalling." (PMID 30338598, 2019). "LncRNA H19 rs217727 could increase cancer risk in overall population, as well as in Asians, subgroups for genotyping based on MassArray, oral squamous cell carcinoma, lung cancer, breast cancer, hospital-based controls and subgroups with a case sample size ≥500." (PMID 31752724, 2019). "A previous study also revealed that E2F6 repressed the oncogenic lncRNA H19 expression in breast cancer cells." (PMID 30614188, 2019). "For instance, H19 is an estrogen-inducible lncRNA and it plays a key role in estrogen-induced cell proliferation in breast cancer cells." (PMID 30355656, 2018). "H19 has been identified as a mediator of breast cancer plasticity during EMT and its reverse process MET, as well as having a role in stemness in prostate cells." (PMID 29757368, 2018). "H19 has been reported to be upregulated and promote cell proliferation in breast cancer, gastric cancer, glioblastoma and lung cancer, while it is downregulated and decreases proliferation in papillary thyroid carcinoma and hepatocellular carcinoma." (PMID 30547791, 2018). "In breast cancer, H19 involves in tumor growth and metastasis through interaction with protein and microRNAs." (PMID 30026672, 2018). "The experimental study demonstrated that H19 served as a biomarker for breast cancer diagnosis and progression." (PMID 30355656, 2018).
breast cancer (continued). "For example, H19 is specific for BRCA among the top 200 miRNA-lncRNA pairs; the down-regulation of H19 significantly decreases breast cancer cell clonogenicity and anchorage-independent growth." (PMID 29715309, 2018). "This transcription factor is essential for cell proliferation and can be upregulated by H19 in pancreatic ductal adenocarcinoma or contrarily activates the promoter of H19 in breast cancer cells." (PMID 30557328, 2018). "For example, lncRNA H19, which has been proved to function as oncogene, is up-regulated in many types of cancer, like breast cancer, liver cancer, or HNSCC." (PMID 30441874, 2018). "H19 promotes proliferation and attenuates apoptosis in breast cancer cells, implicating its role in tumorigenesis and tumor growth." (PMID 29719633, 2018). "Several of these terms suggested strongly that H19 can play an important role in infertility or breast cancer, such as female pregnancy (GO:0007565), female gamete generation (GO:0007292), and adrenal gland development (GO:0030325)." (PMID 30567492, 2018). "Many studies have reported that H19 as an oncogene lncRNA in multiple cancers, such as, colorectal cancer, gastric cancer, breast cancer, bladder cancer, and so on." (PMID 29511035, 2018). "H19 expression has been shown to be involved in solid tumors in a variety of cancers including lung cancer, breast cancer, and gastric cancer." (PMID 28108736, 2017). "Taken together, these results suggest that the ERα-H19-BIK axis plays an important role in contributing to drug resistance in breast cancer chemotherapy." (PMID 29299178, 2017). "For example, Si X et alreported that lncRNA H19 confers chemoresistance in ERα-positive breast cancer through epigenetic silencing of the pro-apoptotic gene BIK." (PMID 29069754, 2017). "Accumulating evidence indicates that H19 gene is an oncogenic lncRNA in bladder and hepatocellular carcinoma and breast cancer." (PMID 27911863, 2017). "The overexpression of H19 in breast cancer cells lines facilitates cell cycle transition G1/S while downregulation of H19 by RNA interference impedes S-phase entry and proliferation." (PMID 29099749, 2017). "H19 lncRNA is highly expressed in a variety of human cancers, including breast cancer, colorectal cancer, hepatocellular carcinoma, and gastric cancer, and its overexpression is often correlated with poor prognosis in cancer patients." (PMID 29190892, 2017). "To identify the potential downstream targets of H19 and let-7 involved in BCSC maintenance, we first examined the expression levels of a panel of core pluripotency factors upon H19 overexpression in breast cancer cells." (PMID 28102845, 2017). "The implication of H19 in tumorigenesis has been reported and H19 is overexpressed in many solid tumors such as prostate, bladder or breast cancers." (PMID 29099749, 2017). "We also evaluated the prognostic ability of high H19 expression in three additional female cancer subtypes including uterine carcinosarcoma (n=57), breast cancer (n=1215), and ovarian cancer (n=266 and n=419) from the TCGA datasets." (PMID 27926484, 2017). "To investigate the relationship between H19 and BCSCs, we assessed the expression of H19 in breast cancer tissues and breast cancer cells." (PMID 28102845, 2017). "The expression of H19 was found to be highly up-regulated in paclitaxel induced ERα-positive resistant breast cancer cell lines MCF-7R and ZR-75-1 (by ∼9-fold and 4-fold, respectively) compared to their parental lines MCF-7S and ZR-75-1S." (PMID 29299178, 2017). "H19 overexpression in breast cancer breaks the homeostatic balance between let-7 and LIN28, leading to the inhibition of let-7 and subsequent elevation of LIN28." (PMID 28102845, 2017). "Consistently, H19 expression was detected at higher levels in breast cancer cells than in breast epithelial cells and stemness-related factors OCT4, SOX2 and NANOG were expressed at higher levels in MDA-MB-231 cells compared with MCF-10A cells." (PMID 28102845, 2017).
breast cancer (continued). "Taken together, these findings evidently suggest that H19 acts as a miRNA sponge to restrict the biological function of let-7 in breast cancer cells." (PMID 28102845, 2017). "By MTT assays, it was observed that both MCF-7R and ZR-75-1R cells showed decreased viability following treatment with paclitaxel, suggesting that H19 contributes to drug resistance in breast cancer." (PMID 29299178, 2017). "They found that suppression of H19 expression sensitized MCF-7S cells to paclitaxel, suggesting that ERα promoted H19 expression in breast cancer cells and that H19 is an important mediator of ERα-induced drug resistance." (PMID 29299178, 2017). "Abnormal expression of H19 has been discovered in a bulk of cancers, including breast cancer, lung cancer, cervical cancer and bladder cancer." (PMID 28230721, 2017). "Here we show that breast cancer stem cells (BCSCs) express high levels of H19, and ectopic overexpression of H19 significantly promotes breast cancer cell clonogenicity, migration and mammosphere-forming ability." (PMID 28102845, 2017). "LIN28 expression was remarkably reduced following H19 depletion by siRNAs in two breast cancer cells." (PMID 28102845, 2017). "The lower availability of let-7 increases the expression of its target, the core pluripotency factor LIN28; LIN28 in turn blocks mature let-7 production and enhances the expression of H19 in breast cancer stem cells." (PMID 29099749, 2017). "H19, an imprinting oncofetal gene, has been shown to be overexpressed in multiple cancer tissues including breast cancer and be an estrogen-regulated gene." (PMID 29190892, 2017). "We showed that H19 is overexpressed in 73% of breast cancer tissues when compared to healthy tissues." (PMID 29099749, 2017). "In the present study, we investigated the role and molecular mechanism of H19 lncRNA in chemoresistance development by using doxorubicin (Dox) resistance in breast cancer cells as a model system." (PMID 29190892, 2017). "In this review, we will focus on the implication of H19, the first identified lncRNA, in human breast cancer." (PMID 29099749, 2017). "To explore the molecular mechanism whereby H19 regulates BCSCs, we first examined the expression level and location of H19 in breast cancer cells." (PMID 28102845, 2017). "Recently, lncRNAs such as lncRNA-ATB, GAS5, HOTAIR, CCAT2, H19, BCAR4, UCA1, LncRNA-ROR and LncRNA-ARA have been implicated in resistance to chemotherapy in breast cancer patients." (PMID 29299178, 2017). "While for H19, studies were including two breast cancer studies, one gastric cancer study, one melanoma study, one ovarian cancer study, and one bladder cancer study." (PMID 28159929, 2017). "Our data also reveal that LIN28 blocks mature let-7 production and, thereby, de-represses H19 expression in breast cancer cells." (PMID 28102845, 2017). "Major findings about H19 and its implication in breast cancer are summarized below in a timeline manner." (PMID 29099749, 2017). "Many studies have confirmed that H19 is re-expressed in many types of solid tumors, such as breast cancer, gastric cancer, and esophageal cancer, and H19 expression is closely related to tumor invasion, metastasis, recurrence and poor prognosis." (PMID 28404885, 2017). "Several investigations have confirmed that H19 is over-expressed in bladder, glioma, thyroid, gastric and breast cancers through various mechanisms, including chromosomal abnormalities, transcription factor binding, and epigenetic alterations." (PMID 29299178, 2017). "In human breast cancer cells lines, H19 upregulates the DNA methyltransferase DNMT1 by sponging miR-152, leading to enhancement of cell proliferation and invasion of the cells." (PMID 29099749, 2017). "Our research has revealed that high expression of H19 in breast cancer attenuates cell apoptosis normally seen in response to chemotherapy." (PMID 27845892, 2016).
breast cancer (continued). "We analyzed data from Barretina's research, filtered from the Oncomine databases, and determined that the expression of H19 increased in parallel with growing resistance to PTX in different breast cancer cell lines." (PMID 27845892, 2016). "Accumulating evidences suggested that H19 was up-regulated in a variety of cancer types, including breast cancer, esophageal cancer, bladder cancer and colorectal cancer." (PMID 27027436, 2016). "For example, an L-FFL motif comprised of the lncRNA H19, the TF MYC and the miRNA miR-29c, and an ceRNA motif comprised of the mRNA COL3A1, the lncRNA H19 and the miRNA miR-29c, were both dysregulated in breast cancer." (PMID 27322142, 2016). "Collectively, we showed that H19 was an important factor contributing to drug resistance in breast cancer, and that epigenetic regulation mediated by H19 and EZH2 participates in the acquisition of chemoresistance." (PMID 27845892, 2016). "We further evaluated the role of H19 in breast cancer chemoresistance by ectopic expression of H19 in the parental cell lines MCF-7S and ZR-75-1S." (PMID 27845892, 2016). "H19 is highly expressed in a majority of human cancers, including breast cancer, colorectal cancer, hepatocellular carcinoma, and gastric cancer, and overexpression of H19 is often correlated with poor prognosis of tumor patients." (PMID 27845892, 2016). "We have shown here that the lncRNA H19 is one of the downstream molecules of ERα in breast cancer cells, and that upregulation of H19 by ERα modulates the apoptosis response to chemotherapy in breast cancer cells." (PMID 27845892, 2016). "Following this confirmation of BIK and NOXA as targets of H19, we evaluated their roles in the drug resistance of breast cancer cells by restoring the expression of BIK and NOXA in MCF-7R cells." (PMID 27845892, 2016). "In breast cancer, H19 overexpression promotes tumor progression and leads to increased cell proliferation due to promoting the G-S transition through positive control by the transcription factor E2F1." (PMID 27608009, 2016). "Inhibition of BIK and NOXA by H19 reduced apoptosis in breast cancer cells and their subsequent sensitivity to drugs." (PMID 27845892, 2016). "For this reason, the high expression of H19 in PTX-resistant breast cancer cells attracted our attention." (PMID 27845892, 2016). "Despite the identification of ERα as the upsteam molecular of H19, we also concerned the expression of ERβ and progesterone receptor (PR) in chemoresistant breast cancer cells." (PMID 27845892, 2016). "These overexpression and knockdown studies all validated BIK and NOXA as important downstream targets of H19, and confirmed a strong involvement of both genes in the H19-mediated PTX resistance of breast cancer cells." (PMID 27845892, 2016). "Vennin and colleagues have shown that an overexpression of H19/miR-675 enhances breast cancer cell aggressiveness, including an increased proliferation and migration rate in vitro, and increases tumor growth and metastasis in vivo." (PMID 27608009, 2016). "In this study, we have examined the role of H19-derived miR-675 in controlling the properties of breast cancer cells." (PMID 26353930, 2015). "All together, our results indicate that H19/mir-675-5p increase the activation of several tyrosine kinase receptors and their downstream signaling pathways in breast cancer cells." (PMID 26353930, 2015). "In MDA-MB-231 breast cancer cells stably overexpressing H19, EGF strongly activated EGFR, Akt and Erk compared to parental cells." (PMID 26353930, 2015). "Because H19 has been shown to have oncogenic effects in breast cancer cells, its expression has been studied in ER+ and triple-negative breast tumors." (PMID 25944846, 2015). "In these efforts, the in situ hybridization technique was used to examine H19 expression in 97 breast cancer tumors." (PMID 25944846, 2015).